MALAT1 (metastasis associated lung adenocarcinoma transcript 1)
Diseases named in the same sentence as MALAT1 in open-access papers (continued):
Sharing a sentence is not in itself a finding about the gene and the disease.
tumor (continued). "A positive correlation was observed between the expression levels of MALAT1 and both capsular formation and tumor size." (PMID 39596302, 2024). "Our findings indicate that A3B engages in selective RNA editing including targeting NEAT1 and MALAT1 long non-coding RNAs that are often highly expressed in tumour cells." (PMID 39322638, 2024). "During extensive tumor cell proliferation, MALAT1 is regulated by multiple signaling pathways and has important roles in invasion and metastasis." (PMID 38585701, 2024). "The overexpression of MALAT1 is correlated with a lower overall survival (OS) rate, worse tumor node metastasis (TNM) stage, larger tumor size, and metastasis in pCCA patients." (PMID 38892191, 2024). "We have previously found that NCAPD3 was highly expressed in PCa and CRC to promote tumor progression through STAT3 upregulation of MALAT1." (PMID 38561330, 2024). "This implies that MALAT-1 stimulates the growth of CC by reversing the tumor-suppressive actions of miR-124." (PMID 38511067, 2024). "MALAT-1 hampers immune processes within the tumor microenvironment by affecting the miR-34a/MICA/B and miR-17-5p/PD-L1/B7–H4 axes in TNBC patients and cell lines." (PMID 38511067, 2024). "In summary, the findings indicate that MALAT-1 significantly facilitates tumor proliferation in NSCLC by regulating the expression of SRSF7." (PMID 38511067, 2024). "They discovered that MALAT-1 expression was elevated in HCC tumor tissues and that MALAT-1 knockdown inhibited HCC cell growth, invasion, and production of pro-inflammatory mediators." (PMID 38511067, 2024). "MALAT1 was found to be increased in tumor tissue according to two datasets but the value of fold change was statistically significant in only one of them (p < 0.01 for GSE43458)." (PMID 39725668, 2024). "In the course of EEC, the PCDH10–Wnt/β-catenin–MALAT1 regulatory axis is a crucial component, and protocadherin 10 (PCDH10), a tumor suppressor gene, decreases the level of MALAT1, which is correlated with the inhibition of tumorigenesis." (PMID 38674413, 2024). "MALAT1 overexpression exhibits tumor-promoting effects through the promotion of tumor cell growth, proliferation, migration, invasion, metastasis, and survival." (PMID 39768127, 2024). "In the TCGA-KIRC cohort, compared to normal tissues, tumor tissues exhibit higher levels of MALAT1, and elevated MALAT1 expression was significantly positively associated with poor prognosis." (PMID 37533434, 2023). "Through these pathways, MALAT1 enhances the function of drug efflux pump in tumor cells, reduces intracellular drug concentration, and leads to drug resistance of tumors." (PMID 36829256, 2023). "MALAT1 knockdown led to Slug inhibition, which in turn led to tumor regression via increased apoptosis and metastasis." (PMID 37245177, 2023). "MALAT1 plays an important regulatory role in the tumour inflammatory environment and increases the proliferation, migration, and epithelial-mesenchymal transition (EMT) process of tumour cells." (PMID 36700118, 2023). "In tumor cells, MALAT1 facilitates EZH2-binding to its target loci, driving H3K27 trimethylation-mediated repression of multiple tumor-suppressor genes, such as E-cadherin, NDRG1, p21, and p27." (PMID 37048060, 2023). "First, lncRNAs can serve as diagnostic markers, they can be used for tumour type differentiation and tumour staging (LUCAT1, MALAT1), and their expression can be related to tumour size or be an early marker of its development (MALAT1)." (PMID 38203731, 2023). "In an in vivo study, high expression of MALAT-1 induced tumor growth, whereas downregulation of MALAT-1 suppressed tumor formation." (PMID 38124072, 2023). "Silencing of MALAT-1 restrains tumor proliferation, invasion and migration, and induces cell apoptosis, leading to repressed tumorigenic process of NSCLC." (PMID 37476194, 2023).
tumor (continued). "It has been shown that MALAT-1 by targeting mir-1271 as a molecular sponge can suppress inhibit its function to facilitate the tumorigenesis and invasion of tumor cells." (PMID 38124072, 2023). "One good example is ‘metastasis associated lung adenocarcinoma transcript 1′ (MALAT1), a tumor-associated lncRNA with known osteogenic effects." (PMID 37947637, 2023). "Recent studies demonstrated that METTL3 indirectly promotes HMGA2 expression by regulating the m6A modification of circHPS5 and MALAT1 in tumor cells." (PMID 36945110, 2023). "MALAT1 induces migration, invasion, angiogenesis, and metastasis, but it was described as a tumor suppressor, too." (PMID 37175800, 2023). "MALAT1 overexpression in the PC tumor microenvironment has also been reported to promote bone metastasis." (PMID 36831169, 2023). "Increasing studies have shown that the lncRNA MALAT1 plays an important regulatory role in tumor proliferation, invasion, metastasis and drug resistance." (PMID 37653482, 2023). "In FL, our study also revealed biological insights that seem to explain the clinical behavior of MALAT1 upregulation in these neoplasms and its relationship to the aggressiveness of the tumors." (PMID 37803049, 2023). "Further experiments revealed that short hairpin RNA (shRNA)‐mediated knockdown of MALAT-1 suppressed tumor cell viability and migration." (PMID 38124072, 2023). "The knockdown of lncRNA MALAT1 using an antisense oligonucleotide technique in a mouse breast cancer model resulted in decreased tumor growth and reduced metastasis." (PMID 37151887, 2023). "Silencing of MALAT1 was also notably correlated with smaller tumor size and longer median survival time of xenograft transplanted mice." (PMID 37047365, 2023). "In HCC, elevation of MALAT1 also mediated tumor growth and DOX resistance via a MALAT1/miR-3129-5p/Nova1 axis." (PMID 37781691, 2023). "Subsequent studies reported that the expression of MALAT1 is an independent prognostic factor and is involved in tumor cell proliferation, metastasis, and epithelial-mesenchymal transition." (PMID 37325561, 2023). "RNA-seq analysis showed that 198 common DEGs were upregulated by MALAT1 knockdown (putative tumor suppressors), and 266 common DEGs were downregulated (putative oncogenes)." (PMID 37667226, 2023). "LncRNA Malat1 induces tumor growth and immune evasion in DLBCL by sponging miR-195 to regulate PD-L1 expression." (PMID 37346034, 2023). "To explore the molecular mechanism of MALAT1 in HCC, we screened target genes associated with MALAT1 (i.e., highly expressed in HCC tumor tissues and positively associated with poor prognosis in HCC patients) from TCGA database and identified the BRF2 gene." (PMID 37653482, 2023). "In a GC study, MALAT1 increased the accumulation of SQSTM1 in tumor cells, which in turn activated NF-κB and increased the expression of IL-6." (PMID 37178254, 2023). "HOTAIR has been reported to be an upstream regulator of MALAT1, and promising results have been obtained from the use of MALAT1 and HOTAIR in regulating oncogenic immune-modulatory proteins CD80 and MSLN in tumor-associated macrophages (TAMs)." (PMID 36997931, 2023). "Further research showed that HIF‐2α can upregulate MALAT1, which can inhibit miR‐216b‐5p, promoting autophagy and increasing tumour cell drug resistance to 5‐FU, DOX and MMC." (PMID 37837401, 2023). "Overexpression of MALAT1 is positively correlated with tumor progression and metastasis in many tumor types, including breast tumors." (PMID 37244966, 2023). "To delineate the possible connection between MALAT1 and HR genes, we explored the possibility of posttranscriptional regulation via miRNAs and found that MALAT1 sequesters miR-421, a tumor suppressor miRNA that regulates the expression of HR genes." (PMID 37812088, 2023). "MALAT-1 has also been linked to the evasion of immune surveillance in RCC, as it can regulate the expression of immune checkpoint molecules and modulate the tumor microenvironment." (PMID 38124072, 2023).
tumor (continued). "A combination of TMZ treatment with MALAT1 silencing inhibited tumor growth and increased survival in the orthotopic xenograft model of GBM." (PMID 37047365, 2023). "Previous research has established that TFEB can be regulated by LncRNA XXYLT1‐AS2 and lncRNA MALAT1, exerting control over the autophagy process in tumour cells." (PMID 37837401, 2023). "Decreased lymph node size and tumor size of brain metastatic lung were observed in patients with GGGT genotype of MALAT1." (PMID 36934373, 2023). "Recently, many studies have shown that alteration of the m6A methylation modification of the lncRNA MALAT1 affects tumor progression." (PMID 37927399, 2023). "This implies that MALAT1 exchange in the TME helps tumor cells establish a tumor-friendly immune response, providing a survival advantage in the stressful TME infiltrated with antitumor immune cells." (PMID 37345170, 2023). "Further studies demonstrated that MALAT1 positively regulated the expression of transcription factor II B‐related factor 2 (BRF2), which was associated with tumor recurrence, large tumor size, and poor prognosis in HCC." (PMID 37653482, 2023). "MALAT1 is a representative onco-lncRNA that stimulates tumor growth and metastasis through multiple mechanisms in different tissues." (PMID 37006626, 2023). "In a tumor xenograft model, silencing of MALAT1 in cisplatin resistant A549 cells led to decreased growth in nude mice (subsequently treated with cisplatin), as compared to non-targeting control." (PMID 37370745, 2023). "TGF-β has also been reported to silence miR-30a-5p through the STAT3/MALAT1 pathway in HNSCC favoring tumor growth." (PMID 37446353, 2023). "MALAT1 can regulate the proliferation, migration and invasion of tumor cells and participate in the malignant transformation of tumors." (PMID 37228500, 2023). "In a study of 113 NSCLC tumor samples, MALAT1 expression was positively correlated with PD-L1 mRNA as well as PD-L1 protein levels." (PMID 37370745, 2023). "The data on MALAT1involvement in tumor processes have aroused a keen interest in studying theoncogenic role of MALAT1 and its involvement in metastatic breast tumor." (PMID 37538803, 2023). "Their findings revealed significantly elevated levels of MALAT-1 expression in both ccRCC tissues and RC cells when compared to adjacent non-tumor tissues and normal human proximal tubule epithelial cells HK-2." (PMID 38124072, 2023). "Further molecular analysis showed that Sel‐GemPac treatment caused suppression of calcium/calmodulin‐dependent protein kinase 1 D (CAMK1D), long non‐coding RNA (lncRNA) GM42418 and MALAT1 in most of the clusters of treated KPC tumour cells." (PMID 38131168, 2023). "MALAT-1 has been shown to promote tumor growth by enhancing cell proliferation and inhibiting apoptosis." (PMID 38124072, 2023). "BRF2 was highly expressed in HCC tumor samples, and a positive relationship was identified between MALAT1 and BRF2 in HCC tumor samples." (PMID 37653482, 2023). "Malat1 has been shown to control the cell cycle in tumor cells by interacting with heterogeneous nuclear ribonucleoprotein C (hnRNP C)." (PMID 36883566, 2023). "LncRNAs, including ANRIL, HOTAIR, MALAT1, SAMMSON, etc., have been implicated to play an essential part in tumor progression, metastasis, and anti-tumor immunity in melanoma via numerous research." (PMID 37770477, 2023). "It has been reported that MALAT1 can support either oncogenesis through gene expression upregulation or tumor suppression through gene expression downregulation." (PMID 37235843, 2023). "The MALAT1 transcript usually has a long half-life: itremains stable for 16 h in human B cells and for 9–12 h in tumor cells." (PMID 37538803, 2023). "Research on triple-negative breast cancer shows a correlation between MALAT1 upregulation, tumor size, and lymph node metastasis." (PMID 37760852, 2023).
tumor (continued). "Tumor suppressor miR-217 blocks EMT by preventing EZH2-mediated H3K27me3 through suppression of the lncRNA MALAT-1 via an Ago2-mediated pathway." (PMID 37245177, 2023). "Concordantly, cell cycle-related or MAPK pathways that were initially observed in both neoplasms involved different sets of MALAT1 positively correlated genes." (PMID 37803049, 2023). "The in vitro studies in cell culturesand studies using tumor xenografts have revealed the contradictory effectsof MALAT1 on tumor cell growth and invasion." (PMID 37538803, 2023). "As an illustrative instance, lncRNA MALAT1 has been documented to exert its influence by instigating alterations in tumor cell metabolism, specifically within the glycometabolic pathways." (PMID 38066437, 2023). "The results showed that MALAT1 was significantly higher in tumor tissues than in adjacent normal tissues." (PMID 35565245, 2022). "In ESCC, miR-101 and miR-217 act as tumor suppressor genes and down-regulate the expression of MALAT1 through an Argonaute2-mediated pathway, thereby inhibiting cell migration and invasion." (PMID 35241975, 2022). "Methyltransferase METTL16 can bind to the triple helix structure at the 3 ‘terminal of lncRNA MALAT1 and influence its structural stability and functional expression, thus participating in the occurrence and development of tumor." (PMID 35719401, 2022). "Two independent studies have shown that the inhibition of MALAT1 expression by different classes of ASOs affects different MM survival pathways and induces tumor cell apoptosis." (PMID 35454868, 2022). "More principal components significantly correlated with MALAT1 than the clinical features of tumor stage and tumor grade, indicating that MALAT1 correlated with methylation variants more strongly than stage or grading did." (PMID 36685103, 2022). "MALAT1 is one of the long non-coding RNAs discovered in the early stage, which is highly expressed in a variety of tumors and closely related to tumor glycometabolism." (PMID 35022030, 2022). "SNHG6 and MALAT1 also demonstrated differential expression between normal tissues and tumor tissues." (PMID 35627262, 2022). "The results indicate that the tumor inhibitory property of MALAT1 can be attributed to the inhibition of the ERK/MAPK-mediated cell growth and MMP2/9-mediated invading processes." (PMID 35935338, 2022). "In vivo assay further validated the tumor-promoting effect of Exo-MALAT1 via regulation of the miR-1-3p/VASP/Rap1 axis." (PMID 35813865, 2022). "Pervious researches reported that MALAT1 facilitate tumor cell proliferation, migration, metastasis, and invasion of blood-tumor-barrier." (PMID 35096427, 2022). "Our results showed that miR-378a-3p acts as a tumor suppressor in CRC-SCs affecting the expression of two lncRNAs MALAT1 and NEAT1." (PMID 35814429, 2022). "As expected, many common tumor‐related lncRNAs, such as MALAT1, NEAT1, HULC, and PVT1, were identified in the H3K27ac chromatin immunoprecipitation sequencing (ChIP‐seq) data." (PMID 36307901, 2022). "Then we found that MALAT1 expression was negatively correlated with miR-503-5p level in tumor tissue." (PMID 35046387, 2022). "An increased level of lncRNA in tumor cells increases their resistance to tamoxifen (lncRNA MALAT1 and CCAT2; miR-221, miR-222, miR,26a, miR-P29a, miR-29b) and trastuzumab (lncRNA, miR-16, and miR-155)." (PMID 36012109, 2022). "Nevertheless, MALAT1 has an important role in tumor progression and ROS can modulate its expression through HIF-1-α." (PMID 36077530, 2022). "The results showed that MALAT1 expression was increased in tumor tissues compared with adjacent normal brain tissues." (PMID 36246567, 2022). "After irradiation, they found that MALAT1 overexpression enhanced tumor cell viability and reduced apoptosis." (PMID 35241975, 2022). "For instance, MALAT1 is upregulated in many types of cancer, driving tumor progression by regulating tumor cell proliferation, metastasis and migration." (PMID 35741059, 2022).
tumor (continued). "Unsurprisingly, some common and vital lncRNAs that promote tumor progression are at the forefront of the H3K27ac signal, such as MALAT1, H19, and CCAT1." (PMID 35311149, 2022). "MALAT1 can enhance glycolysis of tumor cells, inhibit gluconeogenesis, and promote tumor progression." (PMID 35022030, 2022). "The lncRNA metastasis-associated lung adenocarcinoma transcript 1 (MALAT1), also known as nuclear enriched abundant transcript 2 (NEAT2), has been implicated in several tumor-associated cell behaviors." (PMID 35455947, 2022). "Due to the dual function of MALAT1 (oncogenicity or tumor suppression), the development of MALAT1-targeted therapies should be addressed with caution." (PMID 35558512, 2022). "MALAT1 upregulation was apparent in tumor tissues of mice injected with Lv-MALAT1-transduced MCF-7/ADR cells." (PMID 35813865, 2022). "MALAT1 is highly expressed in a variety of tumors and can promote the proliferation, metastasis, and invasion of tumor cells." (PMID 35635083, 2022). "Although there is no report on the ceRNA axis being directly related to OIP5-AS1 or MALAT1, both hsa-miR-23b-3p and hsa-miR-374b-5p are involved in tumor progression." (PMID 36032150, 2022). "mTOR signaling pathway affects tumor proliferation, metastasis, and drug resistance, and MALAT1 mediates the mTOR pathway in multiple cancers." (PMID 35557985, 2022). "qRT-PCR results showed higher expression of MALAT1 in tumor tissues than that in adjacent normal tissues." (PMID 35614065, 2022). "Targeting overexpressed lncRNA, MALAT1, in a mouse model of breast and xenograft models of lung cancers using ASOs significantly reduced tumour growth and metastasis." (PMID 36230680, 2022). "The expression levels for MALAT1 and H19 was downregulated in tumor tissues of 62.5% and 81.25%, respectively, of OSCC patients." (PMID 35723379, 2022). "We analyzed the associations among nine lncRNAs (NEAT1, XIST, NORAD, MALAT1, MIR29B2CHG, LINC00943, AC005332.4, AC092718.4, and LINC01146), risk score, tumor purity, and immune cell infiltration." (PMID 35756601, 2022). "In this study, we show that MiR-423-5p acts as a tumour suppressor through its regulation of MALAT-1 oncogenic functions." (PMID 35016717, 2022). "At the clinical level, higher level of MALAT1 was reported to have an inhibitory effect on miR-202 which is related to large tumor size, poor histological grade, and tumor metastasis in NSCLC." (PMID 35682549, 2022). "On the contrary, the over-expression of MALAT1 plays a dominant role in the processes of tumor cell proliferation and invasion." (PMID 35935338, 2022). "The pro-tumor effects of elevated JMJD2C on NSCLC cells were reversed by silencing MALAT1 or SEPT2, or restoring miR-503-5p." (PMID 35046387, 2022). "Important promoters of tumour angiogenesis can serve as therapeutic targets, including MALAT1, TUG1, LNC00323-003, PVT1, and MIR503HG." (PMID 35052495, 2022). "The aim of this study is to investigate the interlinkage between MALAT1 and HOTAIR and their regulatory activity on immunomodulation by examining the expression profile of CD80 and MSLN in tumor-associated macrophages in the hormonal, HER2+, and TNBC subtypes." (PMID 36387279, 2022). "All these studies suggest that MALAT1 promotes tumor progression by the direct sequestration of the miR-202 RNA." (PMID 35682549, 2022). "Several key molecules in the ceRNA network, such as OIP5-AS1 and MALAT1, have been reported to be related to tumor pathology." (PMID 36032150, 2022). "Specific antisense oligonucleotide treatment against MALAT1 inhibits tumor growth in mouse breast cancer and human NSCLC metastasis models." (PMID 36419933, 2022). "Higher MALAT1 expression was significantly correlated with an advanced tumor stage, a deeper invasion, and a shorter disease-free survival (DFS) time." (PMID 35565245, 2022). "The lncRNAs interaction with PDCDs is mainly assessed in the context of neoplasia indicating the role of MALAT1, MEG3, SNHG14 and LINC00473 in this process." (PMID 35402235, 2022).